CASP8 (caspase 8)
Diseases named in the same sentence as CASP8 in open-access papers (continued):
Sharing a sentence is not in itself a finding about the gene and the disease.
tumor (continued). "In this study, the expression of Bcl-2, Bax, caspase-3, caspase-8 and caspase-9 in tumor tissues were detected by western blotting, and the cell cycle makers and apoptotic index of tumor cells were detected by flow cytometry." (PMID 30670974, 2018). "Overall these data point to Caspase-8 as a modulator of NF-κB activity and provide evidence for a novel function of Caspase-8 as a modulator of tumor microenvironment." (PMID 30501030, 2018). "Because cFLIPL is a crucial competitive inhibitor of caspase-8 activation; its expression can regulate the sensitivity of tumor cells to TRAIL-mediated apoptosis." (PMID 29444104, 2018). "Fas-ligand (FASLG), an upstream activator of pro-apoptotic signalling through Caspase 8 is also upregulated in the immune hot tumours, further highlighting the importance of this pathway." (PMID 30104673, 2018). "The percentage of immunoreactive for CASP3 and CASP8 neurons was different in the region close to tumor invasion compared to the region distally from it." (PMID 30019295, 2018). "Through direct binding to the 3′UTR of caspase 8, miR-24 overexpression inhibited caspase 8 protein expression, thereby promoting tumor cell viability, suppressing TRAIL-induced cell apoptosis, finally promoting the TRAIL resistance of tumor cell." (PMID 29476051, 2018). "We genotyped 7 potentially functional polymorphisms in CASP3, CASP7, CASP8, CASP9, CASP10 genes in 362 HCC patients of receiving surgical resection of HCC tumor." (PMID 28453560, 2017). "As IRF5 can induce p21, Bak, Bax, and Caspase 8, making it a potential candidate of tumor-suppressor." (PMID 28562332, 2017). "The expression levels of cleaved caspase-3, caspase-3, caspase-8, and caspase-9 in tumor and adjacent normal cells in patients were further scored." (PMID 28700659, 2017). "Our data suggest that prior to metabolic adaptation and tumor vessels formation, primary tumor development will be markedly dependent on nutrient availability in the tumor microenvironment which in turn controls the activity of the TRAIL-R/caspase-8 system." (PMID 29212182, 2017). "In vivo experiments in immunodeficient mice demonstrate a requirement for caspase-8 in restraining primary tumor growth of xenografts with p95HER2/611CTF-transformed cells." (PMID 29212182, 2017). "Wilcoxon signed-rank test indicated that the protein levels of cleaved caspase-3, caspase-3, caspase-8, and caspase-9 in tumor tissues were significantly higher compared to those in adjacent normal tissues (all p<0.001)." (PMID 28700659, 2017). "The comparisons of cleaved caspase-3 (CC-3), caspase-3 (C-3), caspase-8 (C-8) and caspase-9 (C-9) expression in the tumor and tumor adjacent normal tissues of OTSCC patients." (PMID 28700659, 2017). "The protein levels of p-JNK, cleaved-caspase-3, and cleaved-caspase-8 in tumor tissues were further investigated by Western blotting analysis, and the results also showed a marked increase in expression of these proteins in the MBIC treatment group." (PMID 28086233, 2017). "Caspase-8 has been shown to have additional functions unrelated to cell death, including T cell activation, cell motility, and tumor metastasis." (PMID 29190740, 2017). "A licensed and commercially available anticancer agent, trabectedin (Yondelis®), induced apoptosis in mononuclear phagocytes (TAMs, monocytes), in a caspase-8 dependent manner, leading to less tumor growth and angiogenesis." (PMID 27886105, 2016). "An increased L1CAM expression lead to a lower expression of caspase-8 and thereby increased apoptotic resistance of tumor cells." (PMID 27174921, 2016).
tumor (continued). "We have previously shown that elevated levels of HPV-16 viral DNA load and surrogate marker p16INK4a expression predict for improved local tumor control and OS in the patients cohort analyzed for Plk3 and pT273 caspase-8 levels in the present study." (PMID 27462786, 2016). "Our findings further indicate a prominent local effect of Plk3 expression and pT273 caspase 8 phosphorylation in response to RCT as exemplified by a significant impact on local tumor control." (PMID 27462786, 2016). "And one mechanism for many therapeutic drugs was to induce tumor cell apoptosis by caspase-8-regulated plasma membrane extrinsic pathway or caspase-9-regulated cell damage intrinsic pathway." (PMID 27015938, 2016). "Tumor cells were treated with either FasL, ceramide analogs, or ceramide analogs in combination with FasL and analyzed for caspase 8 activation." (PMID 27487939, 2016). "We also highlighted a similar methylation profile for healthy prostatic tissue adjacent to the tumour and healthy non prostatic tissue, with the exception of CASP8 and SCGB3A1, which showed a statistically higher methylation in the former." (PMID 27576364, 2016). "Towards this goal, the activity caspase-3 and caspase-8, well-known apoptosis-inducing molecules, were measured in the harvested tumor tissues by western blotting analysis." (PMID 27154307, 2016). "Ceramide enhances FasL-induced activation of the MAPK, NF-κB, and caspase 8 despite induction of potent tumor cell death." (PMID 27487939, 2016). "Targeting A20, a zinc-finger protein over-expressed in MDSCs by small interfering RNA resulted in caspase-3 and caspase-8 dependent apoptosis of MDSCs and increased tumor specific T-cell response, consequently reduced tumor growth in mice." (PMID 27886105, 2016). "Increased levels of caspase 8 were found in both A549 and Tu212 tumor cell lines when treated with dsBPT." (PMID 28033401, 2016). "As expected, marked PARP and cleaved caspase-8 positive staining was observed in the MDM2 knockdown xenograft tumor, while lower expressions of PARP and cleaved caspase-8 were found in G5-DAT62/siScr treated tumor." (PMID 27259273, 2016). "In this situation, increased resistance of tumor cells to apoptotic stimuli, conferred by the CASP8 InsDel or DelDel genotype, turns the balance and becomes a potentially pro-tumorigenic and negative prognostic factor, resulting in decreased OS." (PMID 27507139, 2016). "The death receptor pathway was reported to induce the cell apoptosis pathway through Caspase-8 working on Bid, and then Bid acted on Caspase-3 and Caspase-7 to induce tumor cell apoptosis." (PMID 27833113, 2016). "The extrinsic pathway based on caspase-8 activation strongly participates to apoptosis phenomena in tumor cells." (PMID 25761243, 2015). "Tumor cells can also upregulate cellular FADD-like IL-1β-converting enzyme-inhibitory protein or phosphorylate caspase-8 to inhibit the activation of caspase-8 and block the down-stream signaling pathway of Fas." (PMID 25992623, 2015). "The positive expression of CD95, caspase-8 and caspase-3 was detected in 14 (35%), 14 (35%) and 13 (32.5%) of the 40 tumor specimens, respectively." (PMID 25543761, 2015). "The crucial role of both tumor suppressor genes was further supported by the restoration of TRAIL-sensitized apoptosis upon recombinant overexpression of caspase-8 and DR4 or re-induced expression by DNA demethylation." (PMID 24618889, 2014). "Immunoblotting confirmed the results gained by caspase-3/-7 induction for all executioner caspases in both analyzed tumor cell lines and for caspase-8 in MES-SA cells." (PMID 24618889, 2014). "For example, up-regulation of caspase-8 inhibitors like Flice-like inhibitory protein or inhibition of caspase-8 by Bcl-2 can induce tumor resistance to chemotherapy drugs by decreasing cellular apoptosis." (PMID 25086656, 2014).
tumor (continued). "It has previously been reported that plant-derived flavonoids induce death receptor-mediated caspase-8 activation followed by caspase-3 activation for induction of apoptosis in tumor cells." (PMID 27547487, 2014). "These cells were further treated with the cryoablated tumor extracts, together with the inhibitors of caspase-8, caspase-9, and P2X7 ATP receptor, respectively, for 12 h." (PMID 24818132, 2014). "The correlation between TRAIL-receptor and caspase-8 expression levels and tumor grade showed identical levels of significance in this smaller subgroup." (PMID 24209510, 2013). "The pan-caspase inhibitor Z-VAD and selective inhibitors of caspase-3 and caspase-8 have been shown to increase radition sensitivity resulting in tumor growth delay in vivo." (PMID 23826172, 2013). "To further investigate the mechanism about inhibiting tumor growth, we detected the mRNA levels of caspase-3, caspase-8, and caspase-9 of the tumor tissues from these four groups." (PMID 24307893, 2013). "The subsequent ligation of FasL to its cognate death receptor Fas expressed on target tumor cells results in activation of target cell caspase 8 and cell death." (PMID 26824927, 2013). "In contrast to apoptotic neurons, in our study nuclear caspase-8 was detected in nearly all tumor cells of poorly differentiated HCCs and nuclear caspase-8 expression did not correlate with the apoptosis rate (r = 0.078, p = 0.420)." (PMID 24209510, 2013). "Tumor-specific nuclear localisation of caspase-8 in HCC suggests an apoptosis-independent function of caspase-8 and correlates with patient survival." (PMID 24209510, 2013). "The mRNA levels of caspase-3, caspase-8, and caspase-9 of tumor tissues were reduced in different treatment groups compared with untreated group, particularly in combination group." (PMID 24307893, 2013). "In our cohort, high cytosolic caspase-8 expression correlated with better survival independently from tumor grade, possibly reflecting the higher apoptotic potential of these tumor cells." (PMID 24209510, 2013). "Low cytosolic and high nuclear staining intensity of caspase-8 significantly correlated with impaired survival after partial hepatectomy, which, for cytosolic caspase-8, was independent from tumor grade." (PMID 24209510, 2013). "MHCC97H cells with stable transfection of NET-1shRNA were injected subcutaneously to prepare nude mice model of HCC and Caspase-3, Caspase-8, and Caspase-9 mRNAs of tumor tissues in different groups were examined." (PMID 24307893, 2013). "Of note, variations in the expression of DR4 and DR5 or caspase-8 in different tumor types, different patients and perhaps different cells within one tumor have been observed." (PMID 22690342, 2012). "In A2780WT FLIP cells the apoptotic induction triggered by the association between LBW242, TRAIL and Topotecan is almost completely inhibited, thus suggesting a major role of caspase-8 in the induction of tumor cell death." (PMID 22558117, 2012). "Functional P-gp can confer resistance to activate caspase-8 and -3 dependent apoptosis induced by a range of different stimuli, including tumor necrosis and chemotherapeutic drugs such as docetaxel and vincristine." (PMID 22572929, 2012). "An injectable extract of Semen coicis (a relative of maize) extract displaying anti-tumor activity enhances expression of caspase 8 and induces apoptosis in HepG2 cells." (PMID 22442660, 2012).
tumor (continued). "Further studies revealed that TCS-induced tumor cell apoptosis was attributed to activation of both caspase-8 and caspase-9 regulated pathways." (PMID 22957017, 2012). "The gene targets of this methylation provide candidates for further analysis as potential tumour suppressors, especially components of Caspase 8-dependent apoptosis." (PMID 21712824, 2011). "Caspase 8 is required for TRAIL-induced apoptosis, and it is known that chemotherapeutic agents modulate caspase 8-dependent and mitochondrion-mediated apoptosis pathway to sensitize tumor cells to TRAIL-initiated apoptosis." (PMID 21264227, 2011). "For methylation as a mechanism of sarcomagenesis, two prominent tumor suppressor loci, CDKN2A and RASSF1A, as well as one important apoptosis activator, caspase 8, have been implicated." (PMID 21437220, 2011). "Therapeutic trials to activate CASP8 that had been silenced by methylation have already taken place for other tumour types with some promising results." (PMID 21712824, 2011). "Low caspase 8 levels were previously shown to contribute to rhTRAIL resistance in several cell line models and tumours." (PMID 21487429, 2011). "Our results identified an interplay between the NT-domain, Bcl2 and caspase 8 that helps augment apoptosis and as a consequence, a tumor's response to therapy." (PMID 22069448, 2011). "In most studies using tumor cell lines, the catalytic activity of caspase-8 was dispensable for the stimulation of migration." (PMID 24281211, 2010). "Our data, using caspase 8-specific inhibitors indicates that, in infected tumor cell lines, this is a secondary mechanism, most likely activated in a feedback loop to enhance the apoptotic response." (PMID 20152035, 2010). "Caspase-8 has therefore been suggested as tumor suppressor in the neuroectodermal or neuroendocrine cell lineage, respectively." (PMID 24281211, 2010). "Mechanistic studies indicate that decitabine induces caspase-8 and caspase-9 and sensitizes tumor cells to TRAIL, etoposide, cisplatin and paclitaxel." (PMID 21108789, 2010). "Onconase (ONC), one member of bullfrog RNase A superfamily, displays apoptosis to tumor cells via caspase-9 dependent but caspase-8 independent pathway." (PMID 20089176, 2010). "Univariate analysis showed that there was a significant difference in tumor location and the WI of caspase-8." (PMID 20808443, 2010). "Our results support the notion that caspase-8 is a multifunctional tumor suppressor protein, demonstrating that the DEDs of caspase-8 act to regulate not only cell death, but also differentiation and senescence." (PMID 19924290, 2009). "For example, it is common for tumor cells to express high levels of anti-apoptotic proteins that interrupt the catalytic cascade, or which otherwise alter the threshold of caspase-8 activation required for apoptosis." (PMID 19924290, 2009). "In tumor cells, as well as 293 T cells, caspase-9 activity induced by Vpr or C81 was higher than caspase-8 activity." (PMID 19674438, 2009). "Inhibition of EphB4 expression by specific siRNA or antisense oligonucleotides significantly inhibited tumour cell viability by inducing apoptosis via activation of caspase-8, and also inhibited tumour cell invasion and migration." (PMID 17353927, 2007). "In NB, resistance to TRAIL-induced apoptosis has been preferentially described in MYCN-amplified tumours and correlates with inactivation of caspase 8 gene secondary to gene deletion or silencing through DNA hypermethylation." (PMID 16755292, 2006). "A rapid intracellular ceramide increase has been observed after exposure to γ radiation or exposure to DNA damaging agents, resulting either from the activation of a sphingomyelinase or ceramide synthase, or from caspase-8 activation in different tumor models." (PMID 16545138, 2006).
tumor (continued). "In fact, it has been shown that suppression of caspase 8 expression occurs during the development of NB metastases in vivo, whereas reconstitution of caspase 8 expression potentiated apoptosis and counteracted the spreading of tumour cells." (PMID 16969347, 2006). "In contrast, when TC and T18 cells were induced to apoptosis with TNF-α, only caspase 8 inhibitor inhibited tumor cell apoptosis." (PMID 15907209, 2005). "We noted that 24 h after CDDP application, the apoptotic rate of tumour cells decreased from 93±5 to 75±4% following inhibition of caspase-8, to 85±3% following inhibition of caspase-9, or to 49±6% following inhibition of caspase-3." (PMID 15266324, 2004). "To analyse the involvement of caspases in this rapid vSAG7-mediated tumour cell lysis, we added either ZVAD-fmk (a broad spectrum caspase inhibitor) or IETD-CHO (a specific inhibitor of caspase 8) to the coculture of Vβ6+ T cells and ESb-MP tumour cells." (PMID 11875749, 2002). "Notably, IFN-γ induces iNOS expression and synergistically activates BAX/BAK with caspase-8, intensifying apoptotic effects in tumor cells." (PMID 41601698, 2026). "Based on our autophagy data we determined whether the role of BID in tumor cell killing was due to canonical signaling from death receptor CD95/FADD though caspase 8 to cleave BID, or through a different mechanism." (PMID 40827882, 2025). "In addition, YAP/TAZ controls the expression of pro-inflammatory interleukin-8 (IL-8/CXCL8) in tumor cells undergoing ER stress by a TRAIL-R2/DR5/caspase-8-dependent mechanism." (PMID 39904986, 2025). "Furthermore, the huFasL and caspase-8 mediated gain of function reduced tumor burden significantly than anti-PD-L1 avelumab alone." (PMID 40593750, 2025). "Importantly, treatment of A549 cells with the tankyrase inhibitor significantly sensitized these tumor cells to thapsigargin-induced caspase-8 processing and apoptosis." (PMID 39904986, 2025). "In contrast, the expression or activation state of PANoptosis regulators (e.g., ZBP1, RIPK3, and caspase-8) can be altered by factors such as hypoxia, metabolic stress, and DNA damage in the tumor microenvironment, potentially suppressing or reprogramming PANoptosome formation." (PMID 40422233, 2025). "Further investigation is required to determine whether caspase-8 regulates the inflammatory tumor milieu in favor of tumor promotion or suppression in order to evaluate its clinical relevance as a modulator of the tumor microenvironment." (PMID 40674382, 2025). "We next analyzed the leftover tumor lysates for caspase-8 activity." (PMID 40593750, 2025). "Notably, IFN-γ and TNF-α can synergize to trigger caspase-8–dependent tumor cell death, which is compatible with the increased cytotoxicity observed in our assays." (PMID 41455906, 2025). "Moreover, preincubation of huFasL (but RhFasL) with plasmin followed by addition on tumor cells abolished its cell-killing and caspase-8 activation function." (PMID 40593750, 2025). "Consequently, In malignancies, caspase-8 exerts a dual function by modulating the reorganization of the tumor microenvironment and the expression profile of the tumor." (PMID 40674382, 2025). "In diffuse large B-cell lymphoma, sterile alpha motif and HD domain-containing protein 1 (SAMHD1) deficiency induces PANoptosis and inhibits tumor growth by inducing DNA damage and promoting the expression of STING, which promotes the formation of caspase-8/RIPK3/ASC complex." (PMID 40721869, 2025). "The expressions of Bax, Bcl-2, caspase 8, and caspase 3 in tumor cells were measured using qPCR." (PMID 39062024, 2024).